RPL37P6 (ribosomal protein L37 pseudogene 6)
Gene: Transcribed processed pseudogene on chromosome 8 (56,588,407 to 56,588,700, forward strand). Ensembl gene ENSG00000241431.
Diseases named in the same sentence as RPL37P6 in open-access papers:
RPL37P6 is named in the same sentence as 1 disease in open-access papers, as found by Europe PMC text mining. Sharing a sentence is not in itself a finding about the gene and the disease. The quoted sentences say what the papers report.
cancer (1 paper, 2021). A tumor composed of atypical neoplastic, often pleomorphic cells that invade other tissues. "Many of the genes such as JHY, PLAAT1, PNMA8B, RPL37P6, SNX32, UGGT2 and Y_RNA have not been related to any cancer, yet." (PMID 33672117, 2021).